BTC (betacellulin)
Description:
Growth factor that binds to EGFR, ERBB4 and other EGF receptor family members. Potent mitogen for retinal pigment epithelial cells and vascular smooth muscle cells.
Tractability: Antibody: its Gene Ontology location is reachable by antibodies, with high confidence; UniProt places it where antibodies can reach, with medium confidence; UniProt predicts a signal peptide or a membrane-spanning region.
Gene: Protein-coding gene on chromosome 4 (74,744,759 to 74,794,717, reverse strand). Ensembl gene ENSG00000174808.
Subcellular location: Secreted, extracellular space (Betacellulin); Cell membrane (Probetacellulin)
Pathways (Reactome):
Signal Transduction: Downregulation of ERBB2 signaling; EGFR downregulation; EGFR interacts with phospholipase C-gamma; ERBB2 Activates PTK6 Signaling; ERBB2 Regulates Cell Motility; Estrogen-dependent nuclear events downstream of ESR-membrane signaling; Extra-nuclear estrogen signaling; GAB1 signalosome; GRB2 events in EGFR signaling; GRB2 events in ERBB2 signaling; Nuclear signaling by ERBB4; PI3K events in ERBB2 signaling; PI3K events in ERBB4 signaling; PI5P, PP2A and IER3 Regulate PI3K/AKT Signaling; PIP3 activates AKT signaling; RAF/MAP kinase cascade; SHC1 events in EGFR signaling; SHC1 events in ERBB2 signaling; SHC1 events in ERBB4 signaling; Signaling by EGFR; Signaling by ERBB2; Signaling by ERBB4
Disease: Constitutive Signaling by Aberrant PI3K in Cancer; Inhibition of Signaling by Overexpressed EGFR; Signaling by ERBB2 KD Mutants; Signaling by ERBB2 TMD/JMD mutants
Vesicle-mediated transport: Cargo recognition for clathrin-mediated endocytosis; Clathrin-mediated endocytosis
Gene Ontology:
Molecular function: protein binding; receptor ligand activity; transmembrane receptor protein tyrosine kinase activator activity; epidermal growth factor receptor binding; growth factor activity
Biological process: epidermal growth factor receptor signaling pathway; ERBB4-ERBB4 signaling pathway; positive regulation of cell population proliferation; positive regulation of mitotic nuclear division; ERBB2-EGFR signaling pathway; positive regulation of cell differentiation; positive regulation of fibroblast proliferation; positive regulation of urine volume
Cellular component: extracellular region; clathrin-coated endocytic vesicle membrane; plasma membrane
Genetic constraint (gnomAD): Loss-of-function variants: 8 observed, 11.94 expected, observed/expected ratio (o/e) 0.67, 90% interval 0.39 to 1.21. The upper end of that interval is the gene's LOEUF score, 1.21, which puts it in group 5 of 6, group 1 being the genes least tolerant of losing a copy. Missense variants: 185 observed, 175.15 expected, observed/expected ratio (o/e) 1.06, 90% interval 0.94 to 1.19. Synonymous variants: 74 observed, 66.84 expected, observed/expected ratio (o/e) 1.11, 90% interval 0.92 to 1.34.
Homologues: Orthologues: chimpanzee BTC (98% identical), macaque BTC (87% identical), rabbit BTC (81% identical), pig BTC (80% identical), guinea pig BTC (79% identical), mouse Btc (78% identical), dog BTC (75% identical), rat Btc (71% identical), tropical clawed frog btc (46% identical), zebrafish btc (34% identical). Paralogues in human: TGFA (24% identical), EREG (21% identical), EPGN (19% identical), AREG (18% identical), HBEGF (18% identical).
Diseases named in the same sentence as BTC in open-access papers:
BTC is named in the same sentence as 35 diseases in open-access papers, as found by Europe PMC text mining. Sharing a sentence is not in itself a finding about the gene and the disease. The quoted sentences say what the papers report.
breast cancer (6 papers, 2014 to 2025). A primary or metastatic malignant neoplasm involving the breast. "The study, which included 311 early-stage breast cancer patients, investigated associations between preoperative serum levels of EGFR and EGFR ligands (epidermal growth factor, heparin-binding epidermal growth factor (HBEGF), amphiregulin, transforming growth factor-α and betacellulin) and survival." (PMID 33024132, 2020). "In addition to the mRNA reduction of classical breast cancer subtype markers, expression of ERBB receptor family members HER3 and HER4, as well as the major ligands associated with all major ERBB family signaling molecules (EGF, BTC, HRG) were reduced." (PMID 26522776, 2015). "ADAM17 is involved in the process of breast cancer development and progression, shedding ligands such as TGF-α, AREG, EGFR ligands, and betacellulin and then activating EGFR which promotes breast cancer cell growth and invasion through the PI3K/AKT and Ras/MAPK signaling pathways." (PMID 41050403, 2025). "In cell culture, breast cancer cells with secondary resistance to trastuzumab displayed an up-regulation of mRNA expression for EGF, TGFα, HB-EGF and heregulin, while the expression of AREG mRNA was downregulated and the expression of epiregulin and betacellulin mRNA was unchanged." (PMID 27933395, 2017).
lung cancer (4 papers, 2014 to 2023). A malignant neoplasm involving the lung. "In summary, the present study demonstrated that LPS increased the over-production of BTC and CXCL8 from human lung cancer cells, which could be blocked by anti-BTC neutralizing antibody." (PMID 24629040, 2014). "First, we compared the mRNA levels of common EGFR ligands in lung cancer (HB-EGF, EGF, TGF-α, BTC, AREG, and EREG) by using the gene expression dataset GSE30219, GSE3141, and GSE50081." (PMID 36439487, 2022).
ovarian carcinoma (4 papers, 2013 to 2023). A malignant neoplasm originating from the surface ovarian epithelium. "Another research indicated that ovarian cancer cell migration was induced by betacellulin through EGFR-MEK/ERK signaling." (PMID 36655117, 2023). "To investigate the potential clinical relevance of BTC in ovarian cancer, we queried 489 ovarian cancers from The Cancer Genome Atlas (TCGA) for up-regulation of BTC mRNA above the median." (PMID 27129169, 2016). "Our results suggest that betacellulin induces ovarian cancer migration and Slug-dependent E-cadherin down-regulation via EGFR-mediated MEK-ERK and PI3K-Akt signaling." (PMID 27129169, 2016). "BTC mRNA has been detected in ovarian tumors, however the functional role and clinical significance of BTC in ovarian cancer remains unknown." (PMID 27129169, 2016). "To date, the potential role of BTC in ovarian cancer remains poorly defined." (PMID 27129169, 2016). "In the current study, we tested the hypothesis that betacellulin induces ovarian cancer cell migration by suppressing E-cadherin expression." (PMID 27129169, 2016). "Given that BTC could contribute to poor survival in ovarian cancer, future studies investigating the roles of BTC in ovarian cancer cell invasion, proliferation, apoptosis and angiogenesis would be of interest." (PMID 27129169, 2016). "However, the biological functions and clinical significance of betacellulin in ovarian cancer remain unknown." (PMID 27129169, 2016). "Thus, the roles of BTC and ERBB4 in ovarian cancer are likely complex, and warrant further investigation." (PMID 27129169, 2016). "Treatment of SKOV3 and OVCAR5 ovarian cancer cell lines with betacellulin down-regulated E-cadherin, but not N-cadherin." (PMID 27129169, 2016).
diabetes (2 papers, 2010 to 2014). "This led us to hypothesize a role for betacellulin in the retinal vascular complications associated with diabetes." (PMID 20976146, 2010). "Our results suggest that cleaved betacellulin contributes to increased retinal vascular leakage in diabetes." (PMID 20976146, 2010). "We have compelling evidence that betacellulin can increase retinal vascular permeability and may play a role in the pathogenesis of retinal vascular leakage in diabetes." (PMID 20976146, 2010). "While the exact mechanism by which ADAM-10 is increased in the retinas of diabetics remains to be determined, these results indicate that ADAM-10 may contribute to the cleavage of membrane bound betacellulin that causes increased retinal vascular permeability seen as a complication of the disease." (PMID 20976146, 2010). "The injection of betacellulin into streptozotocin-diabetic and alloxan-diabetic mice stimulates β-cell neogenesis, whereas NGN3 and betacellulin reverse streptozotocin-induced diabetes in vivo." (PMID 25526563, 2014). "Since all patients with diabetes do not develop macular edema, we postulated that a combination of hyperglycemia and increased intravitreous betacellulin might lead to a more severe phenotype." (PMID 20976146, 2010). "Protein levels of the pro-betacellulin as well as its cleaved soluble form were examined by western blot analysis in post-mortem retina tissue from healthy donors, patients with diabetes with no clinical diagnoses of retinopathy and patients with diabetic retinopathy." (PMID 20976146, 2010).
liver cancer (2 papers, 2023 to 2025). An epithelial or non-epithelial malignant neoplasm that arises from the liver. "Since NASH is a precursor of liver cancer, we also performed meta‐analysis of human liver cancer transcriptomes that uncovered betacellulin as a key EGFR‐binding protein upregulated in liver cancer and downregulated by ω3 PUFAs in animals and humans with NASH." (PMID 37859621, 2023). "No immunohistochemical data on liver cancer were available for BTC protein." (PMID 40906438, 2025). "Intriguingly, while the HPA database currently lacks immunohistochemical data for BTC in liver cancer, survival analysis of TCGA-LIHC data revealed no significant survival difference based on BTC expression levels." (PMID 40906438, 2025).
non-alcoholic steatohepatitis (2 papers, 2023 to 2025). "A recent study suggests that the suppression of betacellulin is a mechanism responsible for the anti-inflammatory and anti-fibrotic effects of DHA in non-alcoholic steatohepatitis (NASH), with TGFβ-2 and integrins being the main downstream molecular targets of betacellulin." (PMID 39852375, 2025).
pancreatic ductal adenocarcinoma (2 papers, 2020 to 2023). An infiltrating adenocarcinoma that arises from the epithelial cells of the pancreas. "The BTC‐EGFR‐ERBB4 pathway in pancreatic ductal adenocarcinoma has been well established by several groups and a BTC knock out can partially rescue the cancer progression." (PMID 37859621, 2023).
atopic dermatitis (1 paper, 2025). "Betacellulin (BTC) is one EGFR ligand whose transcript expression is reduced in atopic dermatitis skin lesions." (PMID 40004137, 2025).
beta cell tumor (1 paper, 2020). "Betacellulin (BTC), a member of the epidermal growth factor (EGF) family, was originally isolated from mouse beta cell tumor (betaTC-3) as a growth–promoting factor and is known to be expressed in pancreatic α-cells, β-cells, and duct cells in adult humans." (PMID 33553143, 2020).
chronic periodontitis (1 paper, 2026). A chronic inflammatory process that affects the tissues that surround and support the teeth. "For reference, these correspond to a relatively moderate rank of 204 (FGF2), 645 (AZGP1) and 815 (BTC) among 3242 proteins that have shown any association with periodontitis." (PMID 40913361, 2026). "Further scrutiny examining colocalisation and directionality, and considering known protein interactions and prior evidence, suggested FGF2, AZGP1 and BTC as key targets for periodontitis." (PMID 40913361, 2026). "The Open Targets association scores for these proteins were 0.57 for FGF2, 0.20 for AZGP1 and 0.15 for BTC, providing additional context for their potential biological relevance to periodontitis." (PMID 40913361, 2026). "In addition, our analysis identified BTC, providing new evidence to support the findings of a previous study investigating the expression and role of BTC, a member of the epidermal growth factor family, in chronic periodontitis." (PMID 40913361, 2026). "Therefore, our findings support a potential causal role of FGF2, AZGP1 and BTC in the aetiology of periodontitis, rather than quantifying the precise clinical magnitude of their effects." (PMID 40913361, 2026).
colitis (1 paper, 2023). Inflammation of the colon. "For instance, genes of the EGF-family, such as betacellulin (Btc), previously indicated in ileal growth and homeostasis during health, and amphiregulin (Areg), implicated in intestinal homeostasis during colitis, was induced (Btc) or even de novo expressed (Areg) upon trauma." (PMID 37941007, 2023).
congenital heart disease (1 paper, 2021). A heart disease that is present at birth. "Besides inducing HF via facilitating hyperactive proinflammatory responses, ADAM17 has been implicated along with HB-EGF and betacellulin (BTC), and angiotensin-converting enzyme 2(ACE2) in causing congenital heart diseases and hypertensive-induced HF, respectively." (PMID 34966735, 2021).
COVID-19 (1 paper, 2022). A disease caused by infection with severe acute respiratory syndrome coronavirus 2. "Particularly, this study reports upregulated ADA, BTC, DPP6, EDIL3, LIF, ENTPD2, Flt3L, and LRP1 in severe COVID-19 patients for the first time." (PMID 36428847, 2022).
diabetic macular edema (1 paper, 2010). "Since VEGF has been proposed to be a critical factor in the increase in retinal vascular permeability in proliferative diabetic retinopathy (PDR) and diabetic macular edema (DME), we wanted to determine if the effect of betacellulin was VEGF-dependent." (PMID 20976146, 2010).
diabetic retinopathy (1 paper, 2010). "Western blot analysis of retinas from patients with diabetic retinopathy showed an increase in the active soluble form of betacellulin." (PMID 20976146, 2010).
emphysema (1 paper, 2025). "Several previous studies have linked BTC expression to COPD, and BTC has been found to be higher in ex-smokers with COPD than those without COPD, has been associated with emphysema in alpha-1 antitrypsin deficiency, and has been found to be elevated in acute exacerbations in COPD." (PMID 40798880, 2025).
insulinoma (1 paper, 2011). "Betacellulin (BTC), a member of the epidermal growth factor (EGF) family, was originally identified as a growth-promoting factor in the conditioned medium of a mouse pancreatic beta cell carcinoma (insulinoma) cell line." (PMID 21897861, 2011).
metabolic syndrome (1 paper, 2025). A cluster of metabolic risk factors for CARDIOVASCULAR DISEASES and TYPE 2 DIABETES MELLITUS. "Our results confirm that hepatic betacellulin was overexpressed in the offspring of mothers with metabolic syndrome." (PMID 39852375, 2025).
pancreatic cancer (1 paper, 2020). "To investigate BTC in pancreatic cancer, we generated a BTC knockout mouse model (BTC−/−) and overexpressed BTC in a transgenic mouse model (Btctg/+)." (PMID 32335999, 2020). "The expression of BTC was investigated in human pancreatic cancer specimen." (PMID 32335999, 2020).
pancreatitis (1 paper, 2022). Inflammation of the pancreas. "Because BTC exhibits anti-inflammatory properties in inflammatory conditions such as pancreatitis, it is worth investigating the role of BTC in the pathogenesis of skin inflammatory conditions, including AD." (PMID 36232814, 2022).
Retinal hemorrhage (1 paper, 2010). Bleeding located within the retina. "Intravitreal injections of increasing doses of recombinant soluble betacellulin (0–300 ng) resulted in increased retinal hemorrhage (arrowheads) and increased retinal vascular permeability in a dose dependent manner, similar to that induced by vascular endothelial growth factor (VEGF)." (PMID 20976146, 2010).
Type 2 Diabetes (1 paper, 2006). "We were unable to confirm a role for nonsynonymous variants of betacellulin in the propensity to type 2 diabetes or to impaired insulin secretion." (PMID 16869959, 2006).
viral infections (1 paper, 2023). "The ligand of these receptors is betacellulin (BTC), and a previous study indicated that it might be useful in preventing an excessive fibrotic response to viral infections (such as SARS-CoV) by inhibiting EGFR signaling." (PMID 37936693, 2023).
cancer (18 papers, 2008 to 2024). A tumor composed of atypical neoplastic, often pleomorphic cells that invade other tissues. "During this study, we demonstrated that overexpression of transcription factor DLX2, activation of Smad2/3 signaling, and increased expression of betacellulin were observed in A549 cancer cells surviving the fractionated irradiation." (PMID 33924205, 2021). "BTC is known to also bind to HER4, which has been shown to be associated with better outcome in some cancers, including breast and gastric." (PMID 30899442, 2019). "Several substrates of ADAM15, including EGFR ligands such as HB-EGF, TGFα, amphiregulin, betacellulin, and other factors including Notch, and cytokines have been identified in cancer cells." (PMID 26930657, 2016). "The increased betacellulin (BTC) levels could indicate the increased production of EGF-like proteins to stimulate cancer cell growth." (PMID 37834191, 2023). "Also a member of this family, BTC has been detected in various human cancers, where it has been shown to modulate cancer cell growth, invasion and resistance to targeted therapeutics." (PMID 27129169, 2016). "Overexpression of BTC has been found in many types of human cancers." (PMID 27129169, 2016). "Interestingly, whilst the transcript level of certain genes shifted in a common direction across both clones, including ANKRD17 (down), BTC (up) and MTHFD2C (up), transcript level of the EREG gene, well characterised to be associated with numerous cancers, diverged between clones F and A5." (PMID 34432858, 2021). "It binds several ligands including EGF, betacellulin (BTC) and TGF-α, controls cellular proliferation and invasion and is overexpressed in various cancer types." (PMID 36505413, 2022). "BTC knockout mice have been investigated in cancer and have “no overt defects”, yet decreased endogenous BTC has not been explored in the heart and lungs." (PMID 39065791, 2024). "Previous studies have revealed that betacellulin (BTC) could binds to members of the ErbB family and mediating cancer development." (PMID 36619616, 2022). "High expression of BTC has been previously associated with worse survival in GC; however, there are no studies that relate BTC gene with CDDP resistance in GC cancers." (PMID 31990955, 2020). "Betacellulin was detected by IHC predominantly in the islets of Langerhans and in ducts and acini of normal human pancreas (hNP), in all examined human PDAC samples (6/6), in cancer cells, and the adjacent stroma." (PMID 32335999, 2020). "EGFR is overepressed in many cancer types and activated by a variate of ligands, including besides EGF also the transforming growth factor-alpha (TGFA), heparin-binding EGF-like growth factor (HBEGF), betacellulin (BTC), amphiregulin (AREG) and epiregulin (EREG) and epigen (EPGN)." (PMID 32119655, 2020). "Our study suggests that overproduction of ligands (BTC and NRG2), rather than overproduction of receptors could be the predominant mechanism that the ErbB pathway uses to generate cancer cell proliferation signals." (PMID 18211683, 2008).